SH3TC2 (SH3 domain and tetratricopeptide repeats 2)
Diseases named in the same sentence as SH3TC2 in open-access papers (continued):
Sharing a sentence is not in itself a finding about the gene and the disease.
tumor (4 papers, 2018 to 2022). "We then detected the protein levels of SH3TC2 and two cell-cycle regulators, CDK4 and Cyclin D1, in the tumor tissues from nude mice by Western blot and found that knockdown of SH3TC2 caused a decrease in CDK4 and Cyclin D1." (PMID 36568637, 2022). "Our results showed that SH3TC2 promoted the cell-cycle progression of CRC as well as tumor growth and that SH3TC2 was a new downstream target of the YTHDF1 molecule in CRC." (PMID 36568637, 2022). "After further analysis of the GEO datasets, we found that SH3TC2 in tumor tissue was significantly upregulated in CRC." (PMID 35954399, 2022). "In our cohorts, we found that SH3TC2 was significantly highly expressed in tumor tissue, and high expression also implied poor DFS." (PMID 35954399, 2022). "Stable inhibition of SH3TC2 significantly limited the growth of the tumor, resulting in decreased tumor size, tumor weight, and tumor volume." (PMID 35954399, 2022). "In our cohort, expression of SH3TC2 protein was significantly higher in tumor tissue than in NTT tissue." (PMID 35954399, 2022). "In particular, we noted that SH3TC2 expression was significantly reduced in TGCT tumor samples compared to normal samples, and when the threshold was set to 2, SH3TC2 expression was able to distinguish well between 165 normal samples and 137 tumor samples." (PMID 36568637, 2022). "All these four independent datasets showed that SH3TC2 expression was upregulated in CRC tumor samples." (PMID 36568637, 2022). "The in vivo study implied that downregulation of SH3TC2 significantly impaired tumorigenesis and tumor invasion and increased cell apoptosis." (PMID 35954399, 2022). "Although SH3TC2 is displayed as a prognostic factor across multiple tumor types via bioinformatic analysis, few studies have focused on the prognostic value of SH3TC2." (PMID 35954399, 2022). "Similar to the in vitro results, the in vivo study found that stable slicing of SH3TC2 significantly inhibited tumor growth in a CRC nude mouse model." (PMID 35954399, 2022). "The results of bioinformatics analysis of the GEPIA database implied that higher expression of SH3TC2 in tumor tissue indicates a poor prognosis in CRC patients." (PMID 35954399, 2022). "The results showed that SH3TC2 was differentially expressed between normal and tumor tissues, between tumor and metastatic tissues, and between normal and metastatic tissues." (PMID 35954399, 2022). "In vitro and in vivo experiments revealed that knockdown of SH3TC2 significantly inhibited tumor proliferation and tumorigenesis." (PMID 35954399, 2022). "In our cohort, we found that higher expression of SH3TC2 in tumor tissue indicated poor DFS of CRC patients (HR = 4.71, 95% CI = 1.85–11.99, p = 0.0038)." (PMID 35954399, 2022). "By analyzing the tumor immune microenvironment, we found that expression of SH3TC2 was correlated with T-cell infiltration." (PMID 35954399, 2022). "Recently, the role of SH3TC2 in tumor progression and metastasis has attracted the attention of researchers." (PMID 35954399, 2022). "SH3TC2 is displayed as one of the most prevalent genes and prognostic factors across multiple tumor types." (PMID 32637351, 2020). "Additionally, higher expression of SH3TC2 was found in tumor tissue in our cohort including 40 CRC patients." (PMID 35954399, 2022). "Moreover, we found in the TCGA database and seven GEO datasets that SH3TC2 was significantly highly expressed in tumor tissue." (PMID 35954399, 2022). "Knockdown of SH3TC2 significantly inhibited tumor invasion, migration, and proliferation." (PMID 35954399, 2022). "More importantly, knockdown of SH3TC2 inhibited tumor growth in a CRC mouse model." (PMID 35954399, 2022). "Here, we report that SH3TC2 is a potential tumor driver and clinical biomarker." (PMID 36568637, 2022). "Furthermore, SH3TC2 has been reported to play an important role in tumorigenesis and tumor progression." (PMID 35954399, 2022).
tumor (continued). "Previous study showed that SH3TC2 is one of the most prevalent genes across the tumor tissue." (PMID 30278585, 2018). "SH3TC2 expression may promote CRC tumor progression via the MAPK pathway." (PMID 35954399, 2022). "Expression of SH3TC2 was significantly upregulated in tumor tissue, which may imply poor DFS." (PMID 35954399, 2022). "We are interested to know whether SH3TC2 has some correlation with tumor immune status." (PMID 36568637, 2022). "In addition, the results of a subcutaneous tumorigenesis experiment in nude mice demonstrated that SH3TC2 knockdown significantly inhibited the growth of HCT116 cells in vivo, presenting a smaller tumor volume." (PMID 36568637, 2022). "Overall, SH3TC2 may be a possible marker to optimize the prognosis of CRC and predict tumor recurrence and metastasis." (PMID 35954399, 2022). "Hence, higher expression of SH3TC2 may act as an indicator for tumor recurrence or metastasis but not for patient survival." (PMID 35954399, 2022). "However, expression of SH3TC2 protein was not related to tumor differentiation." (PMID 35954399, 2022).
diseases of the central nervous system (1 paper, 2022). "However, it is important to point out that mutation of SH3TC2 is closely related with diseases of the central nervous system." (PMID 35954399, 2022).
neurological disorders (1 paper, 2022). "SH3 domain and tetrapeptide repeat 2 (SH3TC2) is a protein-encoding gene and has previously been described as a critical signaling hub for neurological disorders." (PMID 35954399, 2022). "SH3TC2 plays a key role in neurological diseases such as Charcot-Marie-Tooth disease type 4C." (PMID 35954399, 2022).
SH3TC2 also shares sentences with these, for which no sentence is quoted: bladder urothelial cancer (2 papers); colon adenocarcinoma (2); neurodegenerative disease (2); pancreatic adenocarcinoma (2); rectum adenocarcinoma (2); sensory ataxia (2); skin cutaneous melanoma (2); testicular germ cell tumor (2); auditory neuropathy (1); breast invasive carcinoma (1); Cerebellar atrophy (1); cholangiocarcinoma (1); chronic respiratory failure (1); clear cell renal cell carcinoma (1); congenital myasthenic syndrome (1); dementia (1); demyelinating (1); glioma (1); hereditary motor and sensory neuropathy (1); hereditary peripheral neuropathy (1); infection (1); Miosis (1); Mydriasis (1); myopathies (1); myopia (1); polyneuropathies (1); primary ciliary dyskinesia (1); rectal cancer (1); Sandhoff disease (1); spinocerebellar ataxias (1).
A further 2 diseases each share a sentence with SH3TC2 in 1 paper.